UBB (ubiquitin B)
Diseases named in the same sentence as UBB in open-access papers (continued):
Sharing a sentence is not in itself a finding about the gene and the disease.
gastric cancer (2 papers, 2020 to 2022). A primary or metastatic malignant neoplasm involving the stomach. "Simultaneous knockdown of UBB and UBC mRNAs induces gastric cancer cell apoptosis, resulting in decreased cell viability, thereby inhibiting gastric cancer cell metastasis." (PMID 35263200, 2022). "Regarding HSF1, its activity is mainly induced in response to different stressful conditions such as heat shock, oxidative stress or proteotoxic stress: this may account for the lack of effect on UBC and UBB gene transcription in HSF1 silenced gastric cancer cells." (PMID 32751694, 2020). "The lack of effect on UBC and UBB gene transcription in HSF1-silenced gastric cancer cells may depend on the fact that HSF1 is a stress-activated TF, while for YY1 we evaluated different target genes in the siYY1-transfected cells and we found that they are differently affected by YY1 knockdown." (PMID 32751694, 2020).
glioma (2 papers, 2021 to 2022). A benign or malignant brain and spinal cord tumor that arises from glial cells (astrocytes, oligodendrocytes, ependymal cells). "The results showed that PSMB6, PSMA5, UBB, and PSMD12 were significantly downregulated, and PSMB10 was significantly upregulated in gliomas." (PMID 34868920, 2021). "This study found the prognostic predictive values of the hypoxia-related genes PSMB10, PSMD12, UBB, PSMA5, and PSMB6 for glioma and provided ideas and entry points for the progress of hypoxia-related glioma." (PMID 34868920, 2021). "The results showed that PSMB6, PSMA5, UBB, and PSMD12 were highly expressed in the glioma tissues, while PSMB10 was lowly expressed in the glioma tissues compared with the normal tissues." (PMID 34868920, 2021). "Notably, PSMB10, PSMD12, UBB, PSMA5, and PSMB6 were found to be independent prognostic predictive markers for glioma." (PMID 34868920, 2021). "PSMB10, PSMD12, UBB, PSMA5, and PSMB6 were found to be independent predictors of glioma prognosis." (PMID 34868920, 2021). "In addition, PSMB6, PSMA5, UBB, and PSMD12 were lowly expressed, while PSMB10 was highly expressed, in the TCGA and GTEx integrated glioma samples and normal samples, which were verified through protein expression levels in the Human Protein Atlas database." (PMID 34868920, 2021). "In this study, our objective was to analyse whether SMB6, PSMD9, UBB, PSMD12, PSMB10, PSMA5, and PSMD14 are independent prognostic factors for glioma." (PMID 34868920, 2021). "Univariate and multifactorial COX regression analyses were used to determine that PSMB10, PSMD12, UBB, PSMA5, and PSMB6 may be independent prognostic factors for gliomas." (PMID 34868920, 2021).
leukemia (2 papers, 2022 to 2023). A malignant (clonal) hematologic disorder, involving hematopoietic stem cells and characterized by the presence of primitive or atypical myeloid or lymphoid cells in the bone marrow and the blood. "There were many leukemia-related genes in the up-regulated genes of K1 group, such as UBB (P=1.56e-50), MIF (P=2.76e-50), DRAP1 (P=1.72e-49), RPS25 (P=1.9e-49), EIF3K (P=4.77e-49), SSNA1 (P=1.27e-48), GPX4 (P=3.01e-48), PHB2 (P=7.13e-48), NME2 (P=2.44e-47) or CFL1 (P=4.07e-47)." (PMID 36408189, 2022).
schizophrenia (2 papers, 2011 to 2024). A major psychotic disorder characterized by abnormalities in the perception or expression of reality. "Ubiquitin B (UBB) expression has been previously identified as a strong correlate of schizophrenia symptoms." (PMID 38648100, 2024). "The top ranked genes in centrality analysis, UBC, ACTB, and UBB, were all abnormally expressed in schizophrenia samples." (PMID 22373040, 2011).
apneic episodes (1 paper, 2023).
bronchopneumonia (1 paper, 2012). Acute inflammation of the walls of the terminal bronchioles that spreads into the peribronchial alveoli and alveolar ducts. "The UBB+1 expression pattern in humans is consistent with the contribution of bronchopneumonia as a cause of death in AD patients." (PMID 22730000, 2012).
Cachexia (1 paper, 2016). Severe weight loss, wasting of muscle, loss of appetite, and general debility related to a chronic disease. "The up-regulation of UBB, FBXO32 (atrogin-1) and TRIM63 (MuRF1) in the irradiated and cachectic muscle tissue suggested that radiation-induced cachexia may share a similar pathway to other muscular atrophic conditions." (PMID 27029502, 2016).
cognitive disorder (1 paper, 2012). A disease affects cognitive processes. "It remains to be analyzed whether other cognitive disorders also display UBB+1 expression and neuronal pathology in central breathing control regions." (PMID 22730000, 2012).
gynecological cancer (1 paper, 2021). "In human gynecological cancer, the expression of UBB is decreased, and the low expression of UBB is associated with the poor survival rate of gynecological cancer." (PMID 34825509, 2021).
lymph node metastases (1 paper, 2024). "Elevated levels of UBB and UBC, particularly in lymph node metastases, suggest a higher risk of disease progression, potentially guiding more aggressive treatment approaches." (PMID 38473264, 2024).
myocardial infarction (1 paper, 2024). Gross necrosis of the myocardium, as a result of interruption of the blood supply to the area, as in coronary thrombosis. "The involvement of genes such as AGPS, MYO9B, PYGB, TOM1, UBA52, and UBB in myocardial infarction is first reported in this study." (PMID 39872885, 2024).
Obesity (1 paper, 2024). Accumulation of substantial excess body fat. "However, with obesity, we observed increased accessibility of genes involved in cell cycle regulation (ATM, CDKN1C, BCL2L11), autophagy (HSPA8, IRF8, PEX5), and protein catabolism (CDC34, CTSB, UBB)." (PMID 39872537, 2024).
proteinopathy (1 paper, 2025). "Two protein components of the ubiquitin-proteasomal system (UPS)—ubiquitin-C-terminal hydrolase (UCHL1), a deubiquitinase, and polyubiquitin-B (UBB) —accumulate in post-MI aggregates, contributing to dysfunctional synaptic activity and proteinopathy that arises after cardiovascular disease." (PMID 40332607, 2025).
Sepsis (1 paper, 2023). Sepsis is defined as life-threatening organ dysfunction caused by a dysregulated host response to infection. "Genes that participate in this pathway and were differentially expressed in our sepsis patients include PSMB1, NFKB2, SEM1, UBB and RELA." (PMID 37731199, 2023).
staphylococcus aureus infection (1 paper, 2021). An infectious process in which the bacteria Staphylococcus aureus is present. "According to the ROC curve, ASB1, UBB, and MKRN1 can effectively act as potential diagnostic markers for distinguishing samples of Staphylococcus aureus infection from healthy counterparts." (PMID 34852788, 2021). "The expression level of UBB, ASB, and MKRN1 could significantly differentiate between Staphylococcus aureus infection and healthy controls based on the ROC curve." (PMID 34852788, 2021).
tumor (32 papers, 2010 to 2025). "The results demonstrated that EEF2, G3BP1, G3BP2, PRPF8, RECQL4, STOML2, and UBB exhibited significantly higher expression levels in the majority of tumor tissues, whereas METTL3 and NR2C2 showed a widespread downregulation trend." (PMID 41341921, 2025). "To investigate and validate the role of UBB in tumor progression in vitro, we conducted assays on cell viability, cell proliferation, cell migration, and cell invasion using RCC cells transfected with UBB overexpression lentivirus (UBB_OE)." (PMID 38467852, 2024). "We can envisage the development of siRNA drugs or small molecule inhibitors based on the UBB gene, thereby reducing its expression level in tumor cells to inhibit tumor adaptability and growth." (PMID 38994370, 2024). "We have demonstrated through in vitro experiments that the proliferation, invasion and migration of tumor cells can be inhibited by decreasing the expression of the UBB gene in tumor cells." (PMID 38994370, 2024). "The results demonstrated a significantly higher UBB expression in tumor tissues compared to normal adjacent tissues (p = 0.001)." (PMID 38473264, 2024). "The in vitro assay and in vivo tumor growth assay revealed that UBB overexpression markedly suppressed tumor growth and intratumoral vascularization." (PMID 38467852, 2024). "The results showed that UBB gene knockdown significantly inhibited the proliferation of tumor cells." (PMID 38994370, 2024). "The DEGs in C1 UBB+ tumor cells were enriched in cytoplasmic translation, ATP synthesis coupled electron transport, mitochondrial ATP synthesis coupled electron transport, oxidative phosphorylation, and the electron transport chain." (PMID 39136009, 2024). "The Wilcoxon rank-sum test showed that ALG8 (P < 0.001) had a higher expression level in tumor tissues compared with normal tissues, while DCTN4 (P < 0.001), DCTN6 (P < 0.001), and UBB (P < 0.001) had lower expression levels in tumor tissues." (PMID 35281472, 2022). "Previous studies emphasize UBB and UBB dependent ubiquitin-proteasomal protein degradation are essential in histone deacetylase inhibitor-induced tumor selectivity." (PMID 33892654, 2021). "The findings reported here are consistent with our previous results, which indicated that UbB is an essential mediator of TSA-induced tumor-selective killing." (PMID 24367661, 2013). "Previous studies highlight the essential role of Ubiquitin B (UbB) and UbB-dependent proteasomal protein degradation in histone deacetylase inhibitor (HDACi) -induced tumor selectivity." (PMID 24367661, 2013). "Among these, UBB stands out due to its established role in immune regulation and tumor progression." (PMID 41281377, 2025). "Collectively, these findings suggest that UBB not only plays a role in tumor progression but may also serve as a viable immunomodulatory target in PCa therapy." (PMID 41281377, 2025). "From these genes, we screened the tumor microenvironment-related gene UBB." (PMID 38467852, 2024). "Furthermore, we also observed a higher UBB expression in lymph node metastatic tissues compared to tumor tissues (p < 0.001) and a significant difference in UBB expression between metastatic tissues and normal tissues (p < 0.001)." (PMID 38473264, 2024). "Inhibiting the ubiquitin UBC in tumors of UBB silencing led to tumor regression." (PMID 37350942, 2023). "UBB or UBC protein was required for some cancer cells to keep tumor features, like myeloma cells." (PMID 37684377, 2023). "In tumor tissues, four protective genes (JAK2, IL2RG, EEF1E1, and UBB) showed relatively low expression in the high‐risk group; in contrast, the expression of four risk genes (EPS8, FOXO1, STAT5A, and PAPPA) was more highly in the high‐risk group than that in the low‐risk group." (PMID 34825509, 2021). "The results suggest that lower UBB and IL-18BP expression may be associated with higher MET and lower CNV levels; evaluating the expression of these genes might therefore aid in early tumor diagnosis and prognosis." (PMID 31257224, 2019).
tumor (continued). "High expression of the UBB gene may enhance the ubiquitination marking and rapid clearance of damaged mitochondria, helping tumor cells effectively remove damaged mitochondria to prevent cellular stress and death, thereby increasing the tumor cells’ adaptability to adverse conditions." (PMID 38994370, 2024). "In the next phase of our research, we plan to verify whether glycitein can enhance the activity of UBB to counteract tumor vasculature and synergize with pazopanib, thereby increasing its sensitivity, thus developing potential therapeutic agents against pazopanib resistance." (PMID 38467852, 2024). "Considering the multifaceted functions of various cytokines and growth factors in the process of tumor angiogenesis, we aimed to investigate whether UBB exerts its influence on angiogenesis by regulating the expression of key cytokines associated with angiogenesis." (PMID 38467852, 2024). "To investigate whether UBB’s tumor suppressor function in ccRCC relies on regulating VEGFA, we conducted concurrent overexpression of VEGFA to counteract its suppression caused by increased UBB levels in RCC cells." (PMID 38467852, 2024). "Interestingly, the knockdown of UBB via small interfering RNA led to inhibition of survival and proliferation of tumor cells by suppressing ubiquitination at multiple sites associated with cancer pathways, and by impeding the ability of tumor cells to overcome increased stress." (PMID 32971786, 2020). "Furthermore, an elevated expression of UbB was shown in the tumor samples of chemotherapy patients." (PMID 24367661, 2013). "The results of the analyses conducted for the TCGA cohort revealed a significantly higher mRNA expression of UBB, UBC, and CTNNB1 in tumor tissues compared to normal tissues (p < 0.0001 for all)." (PMID 38473264, 2024). "In contrast, the expression levels of UBB, UBC, and CTNNB1 in tumor versus normal tissues varied between the GEO cohorts, ranging from being unchanged to being slightly overexpressed or downregulated." (PMID 38473264, 2024). "UBB overexpression considerably suppressed RCC cells proliferation, tumor burden, and angiogenesis both in vitro and in vivo." (PMID 38467852, 2024). "In tumor-infiltrating macrophages we also observed increased activation of cytokine-responsive genes IFITM3, CCR1 and UBB (FDR=10-4), as well as upregulation of genes involved in MHC Class II presentation H2-Aa, H2-Ab1, H2-Eb1 and CD74 (FDR=0.0015)." (PMID 36911698, 2023). "The UCSC Xena database provided the combined TCGA-GTEx cohort, and expression levels of most model genes were differentially expressed between normal and tumor samples, except for SEPT1 and UBB." (PMID 37284314, 2023). "Compared with shRNA-NC group, combined silencing of UBB and UBC (shRNA-B4/C2) inhibited 51.51% of tumor volume, which was more effectively than that of shRNA-B4-transfected group (27.12%) or shRNA-C2-transfected group (45.05%)." (PMID 25820571, 2015). "Furthermore, high expression of the UBB gene may also strengthen the adaptive response of the autophagy pathway under stress conditions such as nutrient deprivation or hypoxia, providing a survival advantage for tumor cells, especially in the challenging tumor microenvironment." (PMID 38994370, 2024). "In TCGA-KIRC database, UBB levels showed a decreasing trend in tumor tissue compared to nontumor tissue, which was consistent with the results for the Gene Expression Omnibus (GEO) datasets (GSE53000, GSE53757)." (PMID 38467852, 2024). "According to the cutoff points established by the Evaluate Cutpoints software, UBB expression was absent in 36 cases (53.7%), while 31 (46.3%) cases demonstrated the presence of UBB expression in tumor tissue." (PMID 38473264, 2024).
tumor (continued). "Among the 25 MRGs exhibiting differential expression between the normal and tumor tissues, only MAP1LC3B, PINK1, PARK2, UBB, and UBC were significantly downregulated in the tumor tissues, while expression of the other genes was significantly upregulated in the tumor samples." (PMID 38155968, 2023).
cancer (23 papers, 2010 to 2025). A tumor composed of atypical neoplastic, often pleomorphic cells that invade other tissues. "Tian and colleagues showed that increased expression of UBB was important for cancer initiation and maintenance of the cancer stem cell state." (PMID 32971786, 2020). "Despite their recognized role in cell survival and proliferation, little is known about the molecular mechanisms regulating UBC and UBB gene expression in cancer cells." (PMID 32751694, 2020). "Consistent with this, the downregulation of ubiquitin by UBB knockdown has been found to have an anticancer effect in several cancer cell lines and xenograft mice." (PMID 30893775, 2019). "Most notably, we showed that UbB is important for maintaining the properties of CSCs and cancer initiation." (PMID 24367661, 2013). "Further study is underway to delineate the role of UbB in the complex regulatory transcriptional programs that control the renewal and maintenance of the cancer stem cell state." (PMID 24367661, 2013). "We evaluated the relationship between UbB expression and chemotherapy by measuring the relative UbB expression of cancer tissue for comparison with the adjacent tissues." (PMID 24367661, 2013). "As a core component of the ubiquitin–proteasome system, UBB is involved in T cell receptor signaling, and downregulation of UBB ubiquitin levels may be a potential therapeutic intervention for cancer." (PMID 41281377, 2025). "Disruptions in UBB expression can further exacerbate the dysregulation of ubiquitin-mediated protein degradation, intensifying the potential impact on prostate cell regulation and cancer progression." (PMID 38473264, 2024). "Therefore, understanding the roles of UBB and UBC in β-Catenin ubiquitination is of paramount importance in deciphering the molecular mechanisms underlying cancer development and exploring potential therapeutic targets." (PMID 38473264, 2024). "Moreover, the knockdown of UBB can significantly decrease the expression of ubiquitin, which is essential for cancer cell growth." (PMID 31242667, 2019). "We found that the maintenance of cancer stem-like characteristics correlated with UbB expression, and silencing UbB expression could reverse the cancer stem cell characteristics." (PMID 24367661, 2013). "Additionally, we found that cancer stem-like cell markers, such as Sox2, Oct4 and Nanog, were down-regulated when UbB was knocked down, suggesting a crosstalk between UbB signaling and the expression of cancer stem-like cell markers." (PMID 24367661, 2013). "This collective body of evidence highlights the potential therapeutic significance of targeting UBB and UBC in cancer treatment and emphasizes the multifaceted factors contributing to the aggressive behavior of various cancer types." (PMID 38473264, 2024). "For example, cancer cell lines with low UBB expression show elevated UBC levels, and inhibiting UBC induces UBB expression." (PMID 37350942, 2023). "Of note, an upregulation of UBB and UBC has also been detected in many human cancer specimens, when compared with paired normal adjacent tissues." (PMID 32751694, 2020). "Both UBB and UBC were found to be upregulated in several cancers and their high expression levels seemed to be essential to sustain the high proliferation rate of cancer cells and to support their ability to overcome increasing cellular stresses." (PMID 32751694, 2020). "We identified Ubiquitin B (UbB), which can covalently link to certain target proteins marking them for degradation by the ubiquitin-proteasome system (UPS), as a mediator of cancer cell apoptosis induced by TSA." (PMID 24367661, 2013). "The transcriptional activity of the protein tyrosine phosphatase non-receptor type 22 (PTPN22) gene increased in all stages of the cancer, but the p-value was only less than 0.05 in CSIV vs. C. Forkhead box O1 (FOXO 1) and ubiquitin B (UBB) are statistically overexpressed in CSI." (PMID 38002011, 2023).
cancer (continued). "UBB is likely to play different roles in different cancer cell types, however, no studies have analyzed the role of UBB." (PMID 37124501, 2023). "UBB and UBC upregulation in several cancers is widely documented." (PMID 32751694, 2020). "Several reports demonstrated the pro-survival role of UBB and UBC in cancer cells." (PMID 32751694, 2020).